LZTS3 (leucine zipper tumor suppressor family member 3)
Description:
May be involved in promoting the maturation of dendritic spines, probably via regulating SIPA1L1 levels at the postsynaptic density of synapses.
Synonyms: ProSAPiP1; KIAA0552
Tractability: PROTAC: its protein half-life has been measured.
Gene: Protein-coding gene on chromosome 20 (3,162,617 to 3,174,504, reverse strand). Ensembl gene ENSG00000088899.
Subcellular location: Synapse; Postsynaptic density; Cell projection, dendritic spine; Cell projection, dendrite; Cytoplasm, cytoskeleton
Subcellular location (Human Protein Atlas): Vesicles
Gene Ontology:
Biological process: regulation of dendritic spine morphogenesis
Cellular component: dendritic spine; postsynaptic density; synapse; cytoskeleton; dendrite
Genetic constraint (gnomAD): Loss-of-function variants: 16 observed, 37.49 expected, observed/expected ratio (o/e) 0.43, 90% interval 0.29 to 0.65. The upper end of that interval is the gene's LOEUF score, 0.65, which puts it in group 2 of 6, group 1 being the genes least tolerant of losing a copy. Missense variants: 816 observed, 837.42 expected, observed/expected ratio (o/e) 0.97, 90% interval 0.92 to 1.03. Synonymous variants: 408 observed, 367.45 expected, observed/expected ratio (o/e) 1.11, 90% interval 1.02 to 1.21.
Homologues: Orthologues: chimpanzee LZTS3 (100% identical), macaque LZTS3 (99% identical), guinea pig LZTS3 (98% identical), dog LZTS3 (98% identical), pig LZTS3 (97% identical), rabbit LZTS3 (97% identical), mouse Lzts3 (95% identical), rat Lzts3 (94% identical), tropical clawed frog lzts3 (53% identical), zebrafish lzts3b (45% identical), zebrafish lzts3a (42% identical), Drosophila melanogaster CG15365 (21% identical), and 1 more. Paralogues in human: LZTS2 (35% identical), LZTS1 (30% identical).
Diseases named in the same sentence as LZTS3 in open-access papers:
LZTS3 is named in the same sentence as 11 diseases in open-access papers, as found by Europe PMC text mining. Sharing a sentence is not in itself a finding about the gene and the disease. The quoted sentences say what the papers report.
lung carcinoma (4 papers, 2021 to 2025). "Leucine zipper tumor suppressor family member 3 (LZTS3) was previously proposed as a potential tumor suppressor in lung cancer and colon cancer 8,9." (PMID 39744581, 2025). "Leucine Zipper Tumor Suppressor Family Member 3 (LZTS3), a well-known tumor suppressor in several cancer types such as lung carcinoma, has sparked interest." (PMID 39744581, 2025). "This study concentrated on the up-expressed PGM5P4-AS1 regulated the cellular processes and the growth of tumors by sponging miR-1275 to up-regulate the expression of LZTS3 in lung cancer." (PMID 33315502, 2021). "High expression of miR-1275 can promote the cell proliferation and migration of lung cancer cells by targeting the leucine zipper putative tumor suppressor 3 (LZTS3), thus, the expression of miR-1257 and LZTS3 was measured by qPCR." (PMID 33315502, 2021). "PGM5P4-AS1 could inhibit lung cancer progression by the up-regulation of the LZTS3 expression via sponging miR-1275." (PMID 33315502, 2021). "In the current study, LZTS3 acted as a target of miR-1275 in lung cancer cells." (PMID 33315502, 2021). "Thirty one down-regulated genes are known to be prognostic markers of lung cancer, 28 of which are of favorable prognosis, such as GDPD1, SLC46A3, CLIC6, LZTS3 or CCNO." (PMID 36544755, 2022).
colorectal cancer (2 papers, 2021 to 2025). A primary or metastatic malignant neoplasm that affects the colon or rectum. "In conclusion, our results suggest a potential oncogenic role of LZTS3 in colorectal cancers, challenging previous perceptions of its function." (PMID 39744581, 2025).
colorectal adenocarcinoma (1 paper, 2025). The most common type of colorectal carcinoma. "Gene enrichment analyses indicated that LZTS3 expression levels correlate with immune checkpoint inhibition, emphasizing the therapeutic potential of LZTS3 for colorectal adenocarcinoma (COAD)." (PMID 39744581, 2025).
cancer (5 papers, 2015 to 2025). A tumor composed of atypical neoplastic, often pleomorphic cells that invade other tissues. "As to the combinational therapies, we compared the sensitivity of three commonly used drugs in targeted therapies between LZTS3-high and LZTS3-low samples achieving from the Genomics of Drug Sensitivity in Cancer (GDSC) database." (PMID 39744581, 2025). "To better understand the expression profiles of LZTS3 in cancers, we analyzed its mRNA expression levels in the most common tumors and also compared with the levels in corresponding normal tissues, respectively." (PMID 39744581, 2025). "LZTS3 expression is related to the reduction of the cytotoxic CD8+ T cells, the early effector playing anti-cancer effects 16,17, and increase of Treg cells, an CD4+ T subpopulation that contributes to tumor immune escape 18,19." (PMID 39744581, 2025). "LZTS3 is a putative tumour suppressor family member, expressed in human oviduct, highly similar to LZTS1 that inhibits cancer cell growth through the regulation of mitosis and it is considered as a roadblock to reprogramming." (PMID 27448656, 2016). "Despite the reported role of LZTS3 as a tumor suppressor in a few cancer types, its expression pattern has not been fully investigated." (PMID 39744581, 2025).
tumor (5 papers, 2016 to 2025). "The Microtubules-associated protein tau (MAPT), alpha-synuclein (SNCA), and leucine zipper tumor suppressor 3 (LZTS3) genes are implicated in neurodegeneration and tumor suppression, respectively." (PMID 39810258, 2025). "Furthermore, upregulation of LZTS3 was notably associated with advanced tumor stages and poorer survival rates." (PMID 39744581, 2025). "The mechanism underlying LZTS3 gene-mediated tumour development inhibition is still unclear." (PMID 39810258, 2025). "Among 23 tissue types, the mean value of LZTS3 expression was decreased in eight of tumor types and increased in eight tumor types." (PMID 39744581, 2025). "Regarding the connection between LZTS3 and tumor immune cells, we next analyzed the expressional correlation between LZTS3 and ICGs in COAD samples." (PMID 39744581, 2025). "Several tumor-related hallmarks had significantly enrichment in the COAD samples with high expression of LZTS3, such as the GOMF_OLFACTORY_RECEPTOR_ACTIVITY." (PMID 39744581, 2025). "The leucine zipper tumour suppressor 3 (LZTS3) gene is found in proteins that regulate gene expression during cell differentiation and tumour growth." (PMID 39810258, 2025). "This bioinformatic study unveils diverse expression patterns of LZTS3 across various tissues, with its expression changes in different tumor types showing inconsistency." (PMID 39744581, 2025). "Subsequently, scholars revealed that LZTS3 regulated the process of cell growth and was thought to be a potential tumor suppressor." (PMID 33315502, 2021). "To assess whether LZTS3 expression can serve as a predictor of metastasis, we scrutinized its expression pattern within the framework of the tumor-node-metastasis (TNM) staging system." (PMID 39744581, 2025). "Our study reveals a correlation between LZTS3 and tumor immune cells." (PMID 39744581, 2025). "It is obvious that the LZTS3 was significantly higher in tumor specimens than in normal specimens." (PMID 39744581, 2025). "Considering the expression level of LZTS3 correlates with tumor progression, gene enrichment analyses suggest that LZTS3 may have potential roles in regulating tumor progression." (PMID 39744581, 2025). "However, in the context of UO, up-regulation of LZTS3 could be understood as activation of a safeguard for tumour suppression in the oviduct." (PMID 27448656, 2016). "Protein level of tumor promoting genes (GPRASP1, APLP1, ALPK3, SPTBN5, PCDHB14, LZTS3, RGL2) were higher in tumor tissues." (PMID 37237274, 2023). "We found that most genes with hazard ratio > 1 (GPRASP1, APLP1, ALPK3, SPTBN5, PCDHB14, LZTS3 and RGL2) have a higher expression in tumor tissues than normal tissues except LINGO1 and LZTS1." (PMID 37237274, 2023).
LZTS3 also shares sentences with these, for which no sentence is quoted: Anxiety (1 paper); colon adenocarcinoma (1); colon cancer (1); esophageal cancer (1); Intellectual disability (1); viral infection (1).